IL22 (interleukin 22)
Diseases named in the same sentence as IL22 in open-access papers (continued):
Sharing a sentence is not in itself a finding about the gene and the disease.
colitis (continued). "Although widely considered as an anti-inflammatory cytokine, IL-22 plays a pathogenic role in the innate colitis model." (PMID 32670290, 2020). "T-cell and macrophage depletion was associated with reduced expression of colitis-associated genes such as Il22, Ifng, Stat1 and Tnfa." (PMID 33127658, 2020). "In this study, we found that Il22−/− mice exhibit increased susceptibility to DSS-induced colitis in the presence of antibiotic-induced dysbiosis." (PMID 33027280, 2020). "In conclusion, TGF-β-signaling in Th17 cells promotes IL-17A+IL-22− and IL-17A+IL-22+ T cells, and tumorigenesis during colitis-associated colon cancer in a mouse model." (PMID 32451418, 2020). "AHR-deficient mice exhibit increased vulnerability to colitis and intestinal C. rodentium infection, which is mainly due to the impaired accumulation of ILC3s and IL-22 production in the gut and a decrease in numbers of intraepithelial lymphocytes (IELs)." (PMID 33193381, 2020). "By other groups and in line with the high susceptibility of AhR−/− mice to development of colitis, we also demonstrated an impaired barrier integrity, low IL-22 levels, and increased colitis susceptibility in mice fed LRD." (PMID 32366032, 2020). "Transfer of CARD9-deficient microbiota into wild type or germ free mice, increased their susceptibility to colitis, with IL-22 being the most highly downregulated gene compared to controls." (PMID 32957545, 2020). "Taken together, these data confirm that dietary AhR ligands ameliorate susceptibility to colitis and show that IL-22, which is critical for barrier homeostasis and also represents an AhR target, inversely correlates with colitis severity." (PMID 32366032, 2020). "Recent study indicated a pathogenic role of IL-22 in the model of spontaneous colitis in IL-10-/- mice, whereas other studies demonstrated a protective role for IL-22 in host defense against C. difficile and C. rodentium mucosal pathogens." (PMID 33488580, 2020). "Any disruption in IL-22 signaling and fucosylation leads to dysbiosis, thus increasing susceptibility to enteric infections and colitis." (PMID 33316984, 2020). "The differentiation of IL-22-producing ILC3 into IFNγ-producing ILC1 has been proven to be highly associated with colitis development in mice." (PMID 30962426, 2019). "In a DSS-induced mouse model of colitis, IL-22 deficiency exacerbates colitis pathogenesis and alters the colonic microbiota to be more colitogenic compared to the control group." (PMID 31189465, 2019). "We demonstrated that symbiotic-flagellin–mediated beneficial effects on the progress of DSS-induced colitis was associated with increased serum levels of IL-22 as well as with a higher proportion of IL-22+ intDCs." (PMID 31206517, 2019). "To explore the possible role of PRRs within EspF in CR-caused lethal colitis in Il22-/- mice, we generated full-length and truncated CR-EspF constructs in pACYC184 plasmid." (PMID 31251784, 2019). "This exacerbation of colitis is associated with reduction of colonic IL‐22‐producing ILC3s, which afford essential protection against intestinal inflammation, and is rescued by exogenous IL‐22." (PMID 29758102, 2018). "For example, T cell-derived IL-22 promotes colitis upon transfer of memory cells into Rag1-deficient recipients." (PMID 29124320, 2018). "The defects of IL-22-induced AMP production in Vil-Cre+ATF3F/F colon fragments further support why Vil-Cre+ATF3F/F mice were also more susceptible to DSS-induced colitis compared to ATF3F/F littermates." (PMID 30455690, 2018). "During experimental colitis, the ablation of IL-22/STAT3 signaling using tyrosine kinase 2 (TIK2) deficient mice exacerbates inflammatory bowel disease." (PMID 30235866, 2018). "Overexpression of IL-22 in the colon of mice with a local gene delivery led to attenuated colitis associated with STAT3 activation and increased production of mucus-associated proteins by epithelial cells." (PMID 29967613, 2018).
colitis (continued). "Despite the beneficial effect of IL-22, continuous activation of the IL-22 pathway increases the risk of colitis-associated cancer, particularly in patients with an extended history of IBD." (PMID 29075900, 2018). "In a Th1-mediated CD model (CD45RB model) that is induced by the adoptive transfer of naïve CD4+ T cells into a immune-deficient host, both T cell-derived and NK cell-derived IL-22 contributed for the suppression of colitis." (PMID 29075900, 2018). "IL-22, another cytokine secreted by Th17 cells, was also upregulated in infiltrated leukocytes in tumor masses of patients with colitis-associated CRC." (PMID 28852270, 2017). "The current study supports that the protective effects of IL-22 as fulminant in DSS-induced colitis in C57BL/6 mice are associated with a decrease in its mRNA expression." (PMID 28584821, 2017). "Collectively, Th17 cell cytokines IL-21 and IL-22 have tumor-promoting effects in colitis-associated CRC." (PMID 28852270, 2017). "One study reported ILC3- and IL-22-dependent progression of colitis-associated colorectal cancer in a mouse model [76•], which indicates the possibility of an involvement of ILC3 in human colorectal cancer." (PMID 27645534, 2016). "Similar findings have been reported in experimental colitis in IL-22 deficiency model with decreased production of antimicrobial peptides RegIIIβ and RegIIIγ." (PMID 27050757, 2016). "In dextran sulfate sodium (DSS)-induced or after CD4+CD45RBhighCD25− transfer colitis models, IL-22-deficient mice showed a more important loss of weight and a decreased survival as compared to WT mice." (PMID 27148267, 2016). "Specifically, T helper 17 cells (Th17), which are a distinct lineage of CD4+ T-cells that produce characteristic cytokines like IL-17 and IL-22, have been implicated in a variety of autoimmune diseases and irAEs, particularly colitis." (PMID 27660709, 2016). "An alteration in the composition of the microbiota was described in IL-22−/− mice, and it largely increases the susceptibility to induced colitis." (PMID 27148267, 2016). "The production of IL-22 by ILCs is induced by IL-23, which is associated with different models of colitis and human IBD." (PMID 27578924, 2016). "For example, IL-22-/- mice are more susceptible to colitis induced by dextran sodium sulfate (DSS) and retinoic acid suppression of DSS-induced colitis was associated with increased IL-22." (PMID 27055194, 2016). "Consistent with this, IL-22 alone was required for the maintenance of bacteria driven innate colitis-associated cancer." (PMID 26780670, 2016). "Expansion of this genus has also been reported in experimental colitis in IL-22 deficiency model associated with defective production of mucosal antimicrobial peptides RegIIIβ and RegIIIγ." (PMID 27050757, 2016). "To confirm that IL-17A/IL-22 produced by CD4+ T cells are indeed pathogenic factors in Tbx21−/− driven T cell transfer colitis, we stimulated intestinal epithelial cells with supernatant of IL-23-activated WT and Tbx21−/− T cells." (PMID 27193261, 2016). "Here we assessed expulsion of H. diminuta, the concomitant immune response and the outcome of DNBS-induced colitis in wild-type (WT) and IL-22 deficient mice (IL-22-/-) ± infection." (PMID 27055194, 2016). "Yet, IL-22 deficient mice develop severe colitis after infection with C. rodentium and show high mortality." (PMID 25799189, 2015). "Transfer of IL-22-competent neutrophils toIL-22-deficient animals protected them from dextran-induced colitis and induced theproduction of antimicrobial peptides, including the mucosal lectin RegIIIβ and thecalcium-binding protein S100A8." (PMID 26108096, 2015). "Production of suppressor cytokines by neutrophils has been described,such as IL-10 in Candida albicans infections and IL-22 associated with inhibition of colitis." (PMID 26108096, 2015).
colitis (continued). "While prior studies showed that IL-22 supports reparative functions in IECs, IL-22 can also mediate inflammation when Treg or IL-10 deficiency causes aberrant macrophage activation and colitis." (PMID 40892518, 2025). "Administration of IL-22 counteracted their colitis susceptibility." (PMID 38722686, 2024). "Interestingly, the functional depletion of both IL-17A and IL-22 exacerbated colitis but had minimal effect on weight loss." (PMID 39462273, 2024). "Given the diminished production of IL-22 by Ire1αΔRorc ILC3s, we next explored whether exogenous IL-22 could mitigate the susceptibility of Ire1αΔRorc mice to DSS-induced colitis." (PMID 38722686, 2024). "The induction of IL-22, a factor demonstrated to bolster host defense against microbes and fortify epithelial barrier integrity, played a pivotal role in regulating microbial dysbiosis associated with colitis and sepsis." (PMID 38397855, 2024). "Moreover, we also demonstrated that the transfer of Card9−/− mice microbiota to wild-type (WT) germ-free (GF) recipients was sufficient to recapitulate the defective IL-22 activation and the increased colitis susceptibility observed in Card9−/− mice." (PMID 38649950, 2024). "Furthermore, various CD1d-expressing cells (e.g., B cells, ILC3s, and macrophages) that can interact with iNKT cells also appear to play protective or pathogenic roles in colitis by producing cytokines (e.g., IL-22 and IL-10) via CD1d-intrinsic signaling." (PMID 38274786, 2023). "The pathogenicity of IL-22 was also observed in the IL-10 receptor-deficient mice model, where elevated macrophage production of IL-23 induced uncontrolled IL-22 expression in ILC3s in the small intestine, leading to colitis." (PMID 37122757, 2023). "Moreover, transfer of the Card9-/- microbiota to germ-free mice leads to increased susceptibility to colitis and lower levels of IL-22, indicating that the unbalanced microbiota drives the immune dysregulation." (PMID 36144238, 2022). "However, IL-22 production that is persistent and dysregulated develops into a pathogen and causes colitis and cancer." (PMID 36601108, 2022). "Indeed DSS-colitis was exacerbated in IL-22-deficient mice and blockade of IL-22 expression delayed recovery from DSS-colitis and exacerbated disease scores." (PMID 36012618, 2022). "This suggests that WT and KO + VC mice recruit a large number of NKp46(+) cells and attenuate DSS-induced inflammation and mucus depletion through the production of a large amount of IL-22, whereas KO mice lack such factors to ameliorate the colitis caused by DSS treatment." (PMID 36142515, 2022). "Likewise, uncontrolled IL-22 was suggested to favor formation of colitis-associated colon cancer, allowing IL-22 modulations only in a highly controlled fashion." (PMID 33869257, 2021). "To study immune-epithelial interactions, we stimulated EpOCs with cytokines previously associated with PSC-UC and with colitis-associated cancer, such as IFNγ and IL-22.11, 33 We confirmed that EpOCs respond to cytokine stimulation with STAT phosphorylation and gene induction." (PMID 33570127, 2021). "The microbiota from mice lacking caspase recruitment domain family member 9 (CARD9), a susceptibility gene for IBD, fail to metabolize tryptophan into AHR ligands, resulting in decreased production of IL-22 by ILC3s and Th22 cells, and increased susceptibility in germ-free recipients to colitis." (PMID 33193381, 2020). "Reduced abundance of Barnesiellaceae in stool is related with colitis in IL-22 deficient mice." (PMID 32595645, 2020). "Interestingly, the dysbiotic flora of IL-22-deficient mice is transmissible to co-housed wild-type mice and can promote their susceptibility to developing colitis." (PMID 33003458, 2020). "Similarly, anti-IL-22 antibody administration restored the symptoms associated with colitis along with the reduction of cancer burden." (PMID 33042126, 2020).
colitis (continued). "Moreover, IL-22-deficient mice exhibit a significantly increased susceptibility to enteric pathogen infection and experimental colitis." (PMID 33381598, 2020). "In addition, a recent study reported that mice with genetic deletion of DR3 specifically on ILC3s were more susceptible to DSS-induced colitis, mainly due to decreased IL-22 from ILC3s57." (PMID 31358760, 2019). "Similarly, IL-23R-dependent IL-22 production caused intestinal inflammation in an innate colitis model that was induced in immune-deficient mice by administration of anti-CD40 mAbs." (PMID 29075900, 2018). "Moreover, Card9−/− mice has an altered microbiota with increased load of gut-resident fungi, and reduced IL-22 production, and the transfer of microbiota from knockout mice to wild-type germ-free mice increases their susceptibility to colitis." (PMID 30008619, 2018). "In both a DSS and RAG adoptive transfer model of colitis, IL-22-deficient mice or mice receiving IL-22-deficient Th cells exhibited enhanced weight loss and colon inflammation as compared to controls indicating that IL-22 has a protective role in multiple models of murine colitis." (PMID 29910812, 2018). "Interestingly, another study showed that IL-22 deficiency leads to altered intestinal microbiota and therefore increases the severity of the disease in a mouse model of experimental colitis." (PMID 28492497, 2017). "The absence of caspase recruitment domain family member 9 (CARD9) results in alteration of microbiota, and the altered microbiota fail to metabolize Trp into Ahr ligands, leading to decreased ILC3 and IL-22 production, and increased susceptibility of the host to colitis." (PMID 29354125, 2017). "Moreover, IL23 driven IL22 producing ILC have been shown to drive bacteria-induced colitis-associated cancer in mice." (PMID 29081776, 2017). "This IL-22-mediated changed microbiota can be transferred to co-housed wild type mice, which subsequently become more susceptible to experimental colitis, suggesting that IL-22 is essential for maintaining the balance between immunity and intestinal microbiota." (PMID 28492497, 2017). "Although IL-17F has largely been ascribed pro-inflammatory roles and may play pathogenic roles in colitis models, it can also synergize with IL-22 to enhance production of anti-microbial peptides." (PMID 29085366, 2017). "The pathogenic role of IL-22 in CD40-triggered colitis may depend on the presence of microbial factors that also influence IL-17A production in the intestine." (PMID 26780670, 2016). "In addition, although prolonged IL-22 production promotes tumor growth in a colitis-associated colon cancer model, it is suggested that IL-22 in the early phase of colitis actually protects against tumor formation." (PMID 28536374, 2016). "To test which effector cytokines were required for colitis induced by T-bet-deficient T cells, we transferred cohorts of Rag1−/− recipients with WT or Tbx21−/− T cells and administered neutralizing antibodies to IL-17A or IL-22." (PMID 27193261, 2016). "Our in vitro experiments suggest that IL-17A and IL-22 synergise to promote intestinal epithelial cell responses, which may in part explain the efficacy of blocking IL-17A or IL-22 in colitis induced by T-bet-deficient T cells." (PMID 27193261, 2016). "Furthermore, Barnesiella was decreased in case of severe colitis in IL-22–deficient and co-housed wild-type mice, suggesting its protective role against inflammation." (PMID 27121964, 2016). "Similar to the in vivo blockade experiments, neutralization of IL-17A or IL-22 was only effective in Tbx21−/− T cells suggesting that augmented cytokine production may be a major driver in colitis induced by T-bet-deficient T cells." (PMID 27193261, 2016). "However, IL-22, mobilized by IL-23, was implicated in the exaggeration of murine colitis induced by anti-CD40 activation in RAG1-/- mice." (PMID 27055194, 2016).
colitis (continued). "Moreover, in multiple experimental mouse models of colitis, administration of Ficz subsequently caused IL-22 induction, whereas administration of an AhR antagonist resulted in more severe colitis with decreased IL-22 production." (PMID 26793707, 2015). "This defect in Il-22 expression, a cytokine known to regulate mucosal wound healing, associated with the increased expression of the pro-inflammatory cytokines Il-1β and Tnf-α, may play a role in the higher colitis susceptibility of GF Card9−/− mice." (PMID 38649950, 2024). "Loss of IL-22 is associated with altered microbiome composition and function as well as reduced AhR activation, suggesting potential involvement in a host-microbe feedback loop in the gut that, combined, may increase susceptibility to colitis." (PMID 36894983, 2023). "IL-22 neutralization or germline deletion of Il22 was associated with a significant reduction in disease features, including reduced colitis scores and reduced colon mass, whereas administration of rIL-22 restored colitis in otherwise disease free TRUC Il22−/− mice." (PMID 36192482, 2022). "While the transfer of Ihh HET CD4+ T cells potently induced colitis, transfer of Ihh KO CD4+ T cells showed strongly diminished colitis indicated by reduced weight loss, reduced colon thickening/shortening and reduced mucosal infiltration of T cells expressing IL-17a, IL-22 and IFNγ in the colon." (PMID 35835905, 2022). "Indeed, IL-22 exerts protection against pathogenic infections, fortifies the intestinal barrier by increasing the expression of tight-junction molecules, and limits mucosal inflammation in colitis." (PMID 36144238, 2022). "Furthermore, IL-22 protects the host from dysbiosis-associated colitis in DSS-treated animals." (PMID 33027280, 2020). "In line with this central role for ILC3 and IL-22 in maintaining intestinal barrier function and tissue homeostasis, loss of IL-22 production by ILC3s in mice results in dysbiosis, barrier disruption and an increased susceptibility to experimental induced colitis." (PMID 32117267, 2020). "In addition, studies in a colitis-associated carcinogenesis mouse model using H. hepaticus infection showed that IL-22 could induce DNA damage via a nitric oxide–dependent mechanism to promote dysplasia." (PMID 31770366, 2019). "The study discovered that the intervention of L. paracaseiL21 resulted in a significant increase in the content of SCFAs and the levels of AhR and HIF1α in the colon of mice with DSS-induced colitis, leading to an upregulation of IL-22 production." (PMID 40806121, 2025). "For example, strain ZDY2013, when combined with isomaltooligosaccharides, enhances the expression of MUC2, tight junction proteins (ZO-1, claudin), and cytokines such as IL-10 and IL-22 in DSS-induced colitis models." (PMID 41141596, 2025). "IL-7, alone or synergizing with IL-1β or IL-23, can also increase IL-22 production in ILC3s via aryl hydrocarbon receptor (AhR) and STAT3, and eventually promote colitis-associated colon cancer progression." (PMID 41467015, 2025). "This activation triggers the aromatic hydrocarbon receptors (AhR)/interleukin-22 (IL-22) axis, effectively reducing colitis symptoms in mice induced by dextran sulfate sodium (DSS)." (PMID 40286060, 2025). "In this experiment, IL-22 was significantly increased in the serum of group M mice during DSS-induced colitis, whereas it was significantly reduced after V9 intervention." (PMID 39926427, 2025). "Given the crucial role of ILC3-derived cytokines in infection-induced colitis, particularly IL-22-mediated clearance of Citrobacter rodentium, we evaluated the consequences of IRF4 deficiency during bacterial challenge." (PMID 40585371, 2025). "And AhR agonists are able to attenuate symptoms of the dextran sulfate sodium (DSS)-induced colitis in model mice by upregulating the expression of IL-22, and this model is highly similar to human UC." (PMID 41019044, 2025).